BRCA1 (BRCA1 DNA repair associated)
Diseases named in the same sentence as BRCA1 in open-access papers (continued):
Sharing a sentence is not in itself a finding about the gene and the disease.
breast cancer (continued). "The reduction in ERα expression observed in adjacent mammary gland and mammary tumors of DMBA-treated animals was consistent with previous reports of reduced ERα in familial BRCA-1 tumors, and sporadic breast cancers with hypermethylated BRCA-1." (PMID 26715507, 2015). "Similar to the mutation spectrum observed in BRCA1/2, protein truncating mutations in PALB2 are associated with breast cancer." (PMID 26489409, 2015). "Our meta-analysis demonstrated that the prevalence of BRCA1 promoter methylation in the breast cancer group was statistically significant elevated in comparison with the control group." (PMID 26643130, 2015). "Recurrent large deletions in BRCA1 have been found in both Mexican and Puerto Rican breast cancer patients." (PMID 26543556, 2015). "The underlying causes of breast cancer development remain very much under investigation, but we now know that the BRCA1 tumor suppressor gene plays an important role in many breast cancers." (PMID 26379698, 2015). "Individuals carrying pathogenic mutations in the BRCA1 and BRCA2 genes have a high lifetime risk of breast cancer." (PMID 25925750, 2015). "Among BRCA1/2 mutation carriers, lower OPG levels were associated with germline mutation locations known to confer an increased breast cancer risk (p = 0.003)." (PMID 26629528, 2015). "In summary, our study demonstrates that Pit-1 transcriptionally represses BRCA1 expression, and sensitizes breast cancer cells to combined treatment with cisplatin and the low calcemic 3-Epi vitamin D metabolite." (PMID 25992773, 2015). "For example, BRCA1 gene is moved to the left because it is connected to several genes overexpressed in basal-like breast cancer subtype." (PMID 26271256, 2015). "We report here the case of a 40 year-old woman carrying a pathogenic germline BRCA1 mutation and diagnosed with a HER2-positive breast cancer." (PMID 26426992, 2015). "In this study, we show that FOXA1 expression is negatively regulated by promoter methylation and silencing, and that BRCA1 regulates FOXA1 expression through suppressing its methylation in both human breast cancer cells and MMECs." (PMID 25531315, 2015). "The efficacy of the software is verified through MDS and clustering and tested with available 11 familial non-BRCA1/BRCA2 breast cancer exome data." (PMID 25905921, 2015). "BRCA1 is an important tumor suppressor gene that plays a crucial role in DNA repair, its lack is observed in 5% of all of breast cancer patients." (PMID 26387133, 2015). "For a panel of 38 breast cancer cell lines, we identified a significant number of surrogate oncogenes in known oncogenes such as BRCA1 and ESR1, lending credence to this approach." (PMID 26779250, 2015). "Another possible explanation is that other factors, besides somatic mutations or decreased mRNA expression (either as a result of copy number variation or epigenetic regulation), act to impair BRCA1 function in sporadic breast cancer." (PMID 25825707, 2015). "We compared the effect of BRCA1 over-expression (by transfection of wild-type (wt) BRCA1 vector) in LCC9 human breast cancer cells with anti-estrogen sensitive MCF-7 cells." (PMID 26575173, 2015). "The study results indicated that BRCA1 positively regulates miR-143-miR-145 expression and miR-143-miR-145 can serve as promising novel biomarkers for breast cancer subtyping." (PMID 25961039, 2015). "Whole-exome sequencing studies conducted in BRCA1/2-negative familial breast cancer patients revealed that each sequenced individual harbored as many as 35 deleterious germline mutations on average." (PMID 25927356, 2015).
breast cancer (continued). "The use of PARPinh in monotherapy to treat patients with breast cancer defective in BRCA1 and/or BRCA2 is a clear example of what is known as synthetic lethality." (PMID 26056084, 2015). "The mutations of the tumor suppressor genes breast cancer 1 (BRCA1) and BRCA2, have been demonstrated to be closely associated with breast cancer." (PMID 25385471, 2015). "BRCA1-derived breast cancers have been shown to leave a characteristic imprinting on the panel of genes expressed by the tumors." (PMID 26061043, 2015). "Both, ER and PR, were expressed in about one-third (ER: 11/38, PR: 11/38) of BRCA1 mutant breast cancer." (PMID 26029931, 2015). "In the present study, we identified two mutations, namely, Q563X (BRCA1) and N3124I (BRCA2), showing a strong founder effect in the Polish patients with a hereditary risk of ovarian/breast cancer." (PMID 25948282, 2015). "In line with our data on differential regulation of CTNNB1 in BRCA1 deficient HCC3153 either expressing both TRα and TRβ or just expressing TRβ (i.e. silenced for THRA) further supports an opposing role of TRs in breast cancer." (PMID 26029931, 2015). "Triple-negative breast cancer lacks the expression of estrogen and progesterone receptors, and human epithelial growth factor 2 receptors (HER2; also known as ErbB2), and shares characteristics with basal-like, claudin-low, and BRCA1-related breast cancer." (PMID 25514463, 2015). "Here we show fish oil derived eicosopanthenoic acid (EPA) that induces eIF2α phosphorylation translationally up-regulates the expression of BRCA1 in human breast cancer cells." (PMID 25762631, 2015). "Germ-line mutations in several genes, such as BRCA1 and BRCA2, are known to increase the risk of breast cancer." (PMID 26468334, 2015). "The knockdown of BRCA1 by lenti-based stable shRNA in BRCA wild-type breast cancer cell line MDA-MB-231 demostrated induction of autophagy as indicated by the expression of LC3-II, an autophagy marker." (PMID 25975349, 2015). "As expected due to their close proximity on chromosome 17q21, BECN1 and BRCA1 are often concordantly deleted or amplified in breast cancers." (PMID 25825707, 2015). "The upregulation of Ahr and Cyp1b1 were paralleled by increased Brca-1 CpG methylation, and reduced expression of BRCA-1 and ERα in mammary tumors induced with DMBA." (PMID 26715507, 2015). "In total we detected 13 BRCA1/2 mutations in our study cohort of 108 patients (12 %; 95 % CI = 6.6–19.7 %), thus reinforcing the important contribution of germline BRCA1 and BRCA2 mutations to inherited breast cancer in this mixed South Africa cohort." (PMID 26577449, 2015). "BRCA1/2 are the most cancer-related genes in breast cancer, they involve in DNA repair, regulation of transcriptional activation and apoptosis." (PMID 25774687, 2015). "Taken together, these data suggest that PIG3 expression was positively associated with BRCA1 expression, and that high PIG3 and/or BRCA1 expression was associated with better OS in human breast cancer patients." (PMID 25797244, 2015). "Germline mutations in BRCA1 and BRCA2 genes are associated with familial breast cancer risk in women, although the majority of breast cancers are sporadic in nature." (PMID 29061935, 2015). "A lower frequency of miR-578 and miR-573 overexpression was observed in BRCA1/2-related breast tumors compared to BRCAX breast cancers (0% vs 55%, p=0.018 and 13% vs 55%, p=0.14), respectively." (PMID 25333258, 2015). "Assessment of cyclin D1, FOXP1, NRP1 and CD99 expression was repeated on a validation cohort of 82 BRCA1 and 65 sporadic basal-like breast cancers." (PMID 26152113, 2015).
breast cancer (continued). "ANXA1 expression was higher in the tumors from BRCA1/2 mutated patients compared to BCAC patients overall: 48.6 % versus 12.4 %, respectively; P <0.0001, and within specific breast cancer subtypes." (PMID 26137966, 2015). "This protocol was applied successfully to the assay and quantitation of DNA sequences related to the breast-cancer BRCA1 gene." (PMID 26102488, 2015). "Furthermore, our results showed that BRCA1 promoter methylation was strongly related to breast cancer patients with high histological grade and lymph node metastasis, revealing that aberrant methylation of BRCA1 promoter may be implicated in the invasion and metastasis of breast cancer." (PMID 26643130, 2015). "In conclusion, this study indicated that BRCA1 promoter methylation appeared to be a useful predictive or prognostic biomarker for breast cancers in clinical assessment." (PMID 26643130, 2015). "Recently, we demonstrated that HUWE1 plays an essential role in regulating the stability of BRCA1, a critical tumor suppressor involved in breast cancer tumorigenesis." (PMID 25883150, 2015). "Germline mutations in the BRCA1 and BRCA2 genes account for 20–25 % of inherited breast cancers and about 10 % of all breast cancer cases." (PMID 26543556, 2015). "Further analysis of genes associated with breast cancer, including ABCB1, BRCA1, GSTP1, IGF2, and TERT, showed a high CM fraction in cancer but non-CM in normal cell lines." (PMID 26659027, 2015). "They showed that the sensitivity of TNBC breast cancer cell lines to PARP inhibitors was increased when BRCA1 was methylated." (PMID 26633365, 2015). "For patients carrying these mutations, approximately 57% of women with a BRCA1 mutation and 49% of women with a BRCA2 mutation will develop breast cancer by the age of 70." (PMID 26870808, 2015). "BRCA1 expression is also known to be lost in some sporadic breast cancers after methylation of the gene promoter (13% of cases), but promoter methylation is rarely observed in tumours of BRCA1 mutation carriers." (PMID 25880076, 2015). "The potential effect of EPA on the BRCA1 expression in vivo was tested in an orthotopic xenograft model of MCF-7 human breast cancer cells." (PMID 25762631, 2015). "The work reported here demonstrates that EPA translationally up-regulates the expression of BRCA1 in human breast cancer cells in vitro and in human breast cancer xenografts." (PMID 25762631, 2015). "The promoter methylation status of this gene was also tested by methylation specific PCR as BRCA1 expression is also known to be lost by this mechanism in some sporadic breast cancers." (PMID 25880076, 2015). "An impressive number of studies have already been conducted to address the association between BRCA1 and/or BRCA2 mutation carriership and breast cancer survival." (PMID 25816289, 2015). "Mutations in BRCA1 and BRCA2 are associated with an increased risk of breast cancer, and is reported to be as high as 80 %, and also associated with ovarian, prostate, pancreatic and male breast cancer." (PMID 26468334, 2015). "BRCA1 and BRCA2 mutation carriers <70 years old face a 57% and 49% (respectively) risk of developing breast cancer." (PMID 26010605, 2015). "Overall, these results show that BRCA1-deficient tumors are significantly enriched for indels in BRCA1 TR genes compared to BRCA2 and sporadic breast cancers." (PMID 25699710, 2015). "Our previous study reported increased levels of angiopoietins and VEGF in tumor tissue of BRCA1/2 carriers, suggesting their contribution in blood vessels sprouting in this familial breast cancer subgroup." (PMID 25333258, 2015).
breast cancer (continued). "Further, TR immunostaining was tested for association with clinicopathological parameters and patient survival in breast cancer samples obtained from BRCA1 carrier vs. sporadic cases." (PMID 26029931, 2015). "In particular, Pit-1 negatively regulates the BRCA1 gene at transcriptional level, and sensitizes breast cancer cells to DNA-damage agents." (PMID 25992773, 2015). "The prevalence of BRCA1 methylation was, especially in mammary tissue, was high in patients with breast cancers compared with healthy females or patients with benign breast diseases." (PMID 26643130, 2015). "For instance, women with defective HR genes BRCA1 and BRCA2 have a significantly increased risk of developing breast cancer or ovarian cancer." (PMID 25374063, 2015). "Standard clinical factors predicted both BRCA mutation status (BRCA1 and BRCA2), notably the number of breast cancers occurring before 50 years and ovarian cancers." (PMID 26047126, 2015). "Although deleterious BRCA1 and BRCA2 mutations constitute the most common breast cancer syndrome, they explain the genetic background in only 1–3 % in sporadic breast cancer populations and about 15 % of familial breast cancer." (PMID 26082817, 2015). "Higher frequency (P < 0.001) of autoantibodies to BRCA1 was found in breast cancer, ovarian cancer, and prostate cancer." (PMID 25865228, 2015). "This was significantly higher autoantibody responses to PARP1 and BRCA1/BRCA2 (especially to PARP1 and BRCA1) in ovarian cancer and breast cancer compared to normal control sera (P < 0.001 and P < 0.01)." (PMID 25865228, 2015). "In conclusion, BRCA1 (Pro871Leu), ERCC1 (Asn118Asn), CYP1B1 (Leu432Val), and SLCO1B3 (rs11045585) are associated with response to NCT in our cohort of breast cancer patients." (PMID 26180747, 2015). "In this study, we investigated the effects of PARP inhibitors in BRCA1 or BRCA2 mutant breast cancer cell lines and in wild-type BRCA cell lines with and without BRCA1 allelic loss." (PMID 25975349, 2015). "BRCA1-miR-143-miR-145 pairs were selected for further experimental validation and showed positive correlation in breast cancer subtypes." (PMID 25961039, 2015). "The present study further investigates BRCA1 gene expression, methylation status and their clinical significance in sporadic breast cancer." (PMID 25789047, 2015). "In our previous study, the role of angiopoietin 2 in BRCA1/2-related breast cancer angiogenesis has been highlighted." (PMID 25333258, 2015). "Inherited germ-line mutations in the high risk genes BRCA1, BRCA2, and PALB2 are identified in approximately 20 percent of these breast cancer families." (PMID 26553136, 2015). "It is thus reasonable to explore BRCA1 epigenetic inactive mechanism and identify a subset of sporadic breast cancer with a specific epigenetic phenotype." (PMID 25789047, 2015). "It has previously been reported that mutations in BRCA1 and BRCA2 genes are linked to breast cancer." (PMID 25885115, 2015). "Silencing of the von Hippel-Lindau (VHL) tumor-suppressor gene occurs by DNA methylation in renal carcinoma, similar to BRCA1 in early breast cancer." (PMID 25908947, 2015). "Previously, we reported that AhR agonists repressed estradiol (E2)-dependent BRCA-1 transcription in human breast cancer cells." (PMID 26715507, 2015). "MiRNA expression profiling was performed on a training set of 43 FFPE familial breast cancer cases divided into 22 BRCA1/2-related and 21 BRCAX." (PMID 25333258, 2015). "Our results reaffirm that specific BRCA1 and BRCA2 mutations found previously to recur in French Canadian breast cancer and breast-ovarian cancer families, also recur in women with ovarian cancer not selected for family history of cancer." (PMID 25884701, 2015).
breast cancer (continued). "Taken together, these data suggest that during breast cancer progression, elevated BRCA1-IRIS expression activates AKT that decreases FOXO3a expression leading to elevated survivin expression." (PMID 25583261, 2015). "As far as we know, this is the most comprehensive description of AS at the BRCA1 locus reported so far in human breast cancer samples." (PMID 25884417, 2015). "In the sporadic form of breast cancer levels of BRCA1 in the excised tumors seems to correlate inversely with the aggressiveness and metastatic potential of the tumors." (PMID 25762631, 2015). "According to previous studies, decreased expression of BRCA1 was detected in certain types of sporadic breast cancer." (PMID 25789047, 2015). "We determined the BRCA1 and BRCA2 status in these cases and report the identification of several rare variants that can potentially explain breast cancer susceptibility in each case analyzed." (PMID 25923920, 2015). "The good correlation between BRCA1 and FOXA1 expression in the panel of breast cancer cell lines led us to explore further the possibility that BRCA1 regulates FOXA1 expression." (PMID 25531315, 2015). "Therefore, we performed a meta-analysis to evaluate whether BRCA1 gene promoter methylation is a risk factor for sporadic breast cancers, and elucidated the association of BRCA1 promoter methylation with clinicopathological characteristics in patients with breast cancer." (PMID 26643130, 2015). "Genotyping of the BsmI and FokI SNPs was performed by PCR-based restriction fragment length polymorphism (RFLP) analysis of 463 genetically enriched female breast cancer cases with known BRCA1/2 status and in 1,012 controls from Pakistan." (PMID 26517870, 2015). "We found that Pit-1 negatively regulated BRCA1 transcription in breast cancer cells, and that Pit-1 inversely correlated with BRCA1 mRNA levels in human breast tumors samples, which is in line with other microarray datasets." (PMID 25992773, 2015). "Mutations in genes such as BRCA1 and BRCA2 lead to autosomal dominant inherited cancer susceptibility and confer a high lifetime risk of breast cancer, as well as ovarian and other cancers." (PMID 26577449, 2015). "A number of studies have analysed the methylation status of BRCA1, a key player in breast cancer and TNBC." (PMID 26633365, 2015). "Our study reaffirms that specific BRCA1 and BRCA2 mutations found previously to recur in French Canadian breast cancer and breast-ovarian cancer families, also recur in women with ovarian cancer not selected for family history of cancer." (PMID 25884701, 2015). "We show that Pit-1 inhibits BRCA1 gene expression and sensitizes breast cancer cells to DNA-damage agents, such as cisplatin." (PMID 25992773, 2015). "These in vivo data provide further proof that DNA methylation is a major mechanism for repressing FOXA1 expression in familial breast cancers and confirm a role for BRCA1 in regulating FOXA1 methylation and expression." (PMID 25531315, 2015). "The rare germline pathogenic BRCA1 mutations increase the risk of breast and ovarian cancer to approximately 80% and 60%, respectively, whereas BRCA2 mutations increase breast cancer risk to more than 80% by the age of 80." (PMID 25948282, 2015). "C#2 also upregulated BRCA1 expression, further demonstrating that phosphorylation of eIF2α and reducing the amount of the eIF2·GTP·Met-tRNAi ternary complex induces expression of BRCA1 in breast cancer cells." (PMID 25762631, 2015). "In contrast, prior studies have studied BRCA1 function in either human breast cancer cell lines or mouse embryonic stem cells." (PMID 26246475, 2015). "For example breast cancer susceptibility mutation BRCA contains two genes; in CGMD, BRCA is included as cancer mutation and each of characterized genes BRCA1 and BRCA2 are considered as two independent genes." (PMID 26160459, 2015).